ACAD10 (acyl-CoA dehydrogenase family member 10)
Description:
Acyl-CoA dehydrogenase only active with R- and S-2-methyl-C15-CoA.
Synonyms: MGC5601
Tractability: Small molecule: a high-quality ligand is known. PROTAC: ubiquitination databases record sites on it; its protein half-life has been measured; a small molecule that binds it is known.
Target class: Enzyme; Oxidoreductase
Gene: Protein-coding gene on chromosome 12 (111,686,037 to 111,757,125, forward strand). Ensembl gene ENSG00000111271.
Pathways (Reactome):
Metabolism: Mitochondrial Fatty Acid Beta-Oxidation
Gene Ontology:
Molecular function: acyl-CoA dehydrogenase activity; kinase activity; flavin adenine dinucleotide binding; oxidoreductase activity, acting on the CH-CH group of donors
Biological process: fatty acid catabolic process; fatty acid beta-oxidation; fatty acid beta-oxidation using acyl-CoA dehydrogenase
Cellular component: mitochondrion; cytoplasm; mitochondrial matrix
Genetic constraint (gnomAD): Loss-of-function variants: 111 observed, 123.81 expected, observed/expected ratio (o/e) 0.9, 90% interval 0.77 to 1.05. The upper end of that interval is the gene's LOEUF score, 1.05, which puts it in group 4 of 6, group 1 being the genes least tolerant of losing a copy. Missense variants: 1,249 observed, 1,399.6 expected, observed/expected ratio (o/e) 0.89, 90% interval 0.85 to 0.94. Synonymous variants: 485 observed, 534.63 expected, observed/expected ratio (o/e) 0.91, 90% interval 0.84 to 0.98.
Homologues: Orthologues: chimpanzee ACAD10 (99% identical), macaque ACAD10 (96% identical), guinea pig ACAD10 (84% identical), pig ACAD10 (83% identical), rabbit ACAD10 (82% identical), mouse Acad10 (80% identical), rat Acad10 (77% identical), tropical clawed frog acad10 (65% identical), mouse Acad12 (38% identical), Caenorhabditis elegans acdh-1 (9% identical), Caenorhabditis elegans acdh-8 (9% identical), Caenorhabditis elegans acdh-10 (9% identical), and 5 more. Paralogues in human: ACAD11 (34% identical), ACADVL (11% identical), ACADS (10% identical), ACADSB (10% identical), ACAD9 (10% identical), ACADM (10% identical), ACADL (9% identical), ACAD8 (9% identical), IVD (9% identical), GCDH (8% identical), ACOX3 (7% identical), ACOX2 (7% identical), and 2 more.
Diseases named in the same sentence as ACAD10 in open-access papers:
ACAD10 is named in the same sentence as 19 diseases in open-access papers, as found by Europe PMC text mining. Sharing a sentence is not in itself a finding about the gene and the disease. The quoted sentences say what the papers report.
Hypertension (5 papers, 2017 to 2025). The presence of chronic increased pressure in the systemic arterial system. "Genome wide association studies have revealed that single nucleotide polymorphisms in ACAD10 are strongly associated with hypertension, diabetes, weight gain or glaucoma." (PMID 39174697, 2024). "Therefore, it is possible that the association of ACAD10 with hypertension is partly due to the dysregulation of the mitochondrial oxidation process." (PMID 34828409, 2021). "ALDH2 was previously shown to be associated with BP and hypertension The acyl-CoA dehydrogenase family member 10 gene (ACAD10) is located at 12q24.12 (NCBI Gene), is ubiquitously expressed (The Human Protein Atlas), and activates the β-oxidation of fatty acids in mitochondria (NCBI Gene)." (PMID 28562329, 2017). "ACAD10 has previously been identified as one of the candidate causal genes for CAD, stroke, and hypertension, a common risk factor for CVDs48." (PMID 41027922, 2025). "Among the results, the rs11066015 of ACAD10 had a sex-specific effect on the development of hypertension." (PMID 34828409, 2021). "The heterogeneity analysis revealed that the rs11066015 of ACAD10 was a significant locus that had sex-specific genetic effects on the development of hypertension." (PMID 34828409, 2021). "ACAD10 has not previously been associated with BP or hypertension, although rs11066015 of this gene was shown to be related to coronary artery disease." (PMID 28562329, 2017).
coronary artery disease (3 papers, 2016 to 2025). "Previous studies have reported that ACAD10 is associated with coronary artery disease and T2D, and it has been suggested that the effect of ACAD10 on T2D might be mediated by disordered insulin resistance that is due to abnormal lipid oxidation." (PMID 26833210, 2016).
glaucoma (3 papers, 2022 to 2024). Increased pressure in the eyeball due to obstruction of the outflow of aqueous humor. "The start-loss variant, rs753877638, in ACAD10 is significantly associated with both IOP (P = 1.30 × 10−10, beta = 8.41, AF = 0.003%) and glaucoma (P = 3.68 × 10−4) in UKB." (PMID 36450729, 2022). "BOD1L1, RALYL, LDB3, ACAD10, CDK11A, and DPF3 are also associated with glaucoma topical treatments (P < 1 × 10−5)." (PMID 36450729, 2022). "In addition, a recent study using whole-exome sequencing identified rare variants and genes associated with IOP and glaucoma, including BOD1L1, ACAD10, and HLA-B, demonstrating the power of including and aggregating rare variants." (PMID 36980914, 2023).
gout (3 papers, 2020 to 2023). A condition characterized by painful swelling of the joints, which is caused by deposition of urate crystals. "From ROL type gout, rs4148155 of ABCG2 (pmeta=9.75×10–46; OR=2.79) and rs11066008 of ACAD10 (ALDH2) (pmeta=4.20×10–12; OR=1.79) were revealed to have an association." (PMID 32238385, 2020).
Insulin resistance (3 papers, 2016 to 2024). Increased resistance towards insulin, that is, diminished effectiveness of insulin in reducing blood glucose levels. "Acyl-CoA dehydrogenase 10 (Acad10)-deficient mice develop impaired glucose tolerance, peripheral insulin resistance, and abnormal weight gain." (PMID 33301490, 2020). "In the initial description of an ACAD10 knockout mouse model, diet induced obesity and insulin resistance were reported." (PMID 39174697, 2024).
diabetes (2 papers, 2020 to 2024). "ACAD10 deficiency has not yet been identified in humans, and our findings leave open the possibility of a wide variety of phenotypes including fasting or stress induce rhabdomyolysis, obesity, and type 2 diabetes mellitus, and primarily neurologic symptoms." (PMID 33301490, 2020).
type 2 diabetes (2 papers, 2020). "Consistent with this notion, Bian and colleagues proposed that ACAD10 variation in Pima Indians may increase susceptibility to type 2 diabetes and that this effect may be mediated by impairment of insulin sensitivity via abnormal lipid oxidation." (PMID 32196924, 2020).
Anxiety (1 paper, 2020). Intense feelings of nervousness, tension, or panic often arise in response to interpersonal stresses. "The constellation of reduced exploratory activity without evidence of motor impairment and increased avoidance of open and, thus, more anxiety-inducing spaces suggests that ACAD10 deficiency may be a contributing factor to altered neurological functioning leading to elevated anxiety levels." (PMID 33301490, 2020).
hepatoblastoma (1 paper, 2024). Hepatoblastoma (HB) is a malignant hepatic tumor and is the most common pediatric liver cancer. "In contrast, we detected a strong band with an apparent molecular weight of ± 60 kDa, which was absent when we inactivated ACAD10 in the HepG2 hepatoblastoma cell line." (PMID 39174697, 2024).
hyperuricemia (1 paper, 2018). An abnormally high level of uric acid. "Of these SNVs, nine are located at seven gene loci (DDX39B, NFKBIL1, CDC42BPG, CDC63, BRAP, ACAD10, and PCNX3) that might be novel susceptibility loci for hyperuricemia." (PMID 29124443, 2018).
cancer (3 papers, 2017 to 2025). A tumor composed of atypical neoplastic, often pleomorphic cells that invade other tissues. "Additionally, ACOX3, ACAD9, ACAD10, ACOT1, ACOT8, and DECR2 displayed positive associations with PEBP1/STK11 co-expression across various cancer types, highlighting a potential involvement in enhancing fatty acid metabolism in the context of PEBP1/STK11 expression." (PMID 40806276, 2025).
infection (2 papers, 2010 to 2025). The state of being infected such as from the introduction of a foreign agent such as serum, vaccine, antigenic substance or organism. "Cluster 1 which represents genes that are mostly reduced through the entire course of infection includes many metabolism related genes (e.g., Aldh2, Acad12, Acad10, P2rx7, Ldhb and others)." (PMID 39920132, 2025).
ACAD10 also shares sentences with these, for which no sentence is quoted: Obesity (2 papers); atrial fibrillation (1); cardiovascular diseases (1); Impaired glucose tolerance (1); myocardial infarction (1); rhabdomyolysis (1); Stroke (1).